ATM (ATM serine/threonine kinase)
Description:
Serine/threonine protein kinase which activates checkpoint signaling upon double strand breaks (DSBs), apoptosis and genotoxic stresses such as ionizing ultraviolet A light (UVA), thereby acting as a DNA damage sensor. Recognizes the substrate consensus sequence [ST]-Q. Phosphorylates 'Ser-139' of histone variant H2AX at double strand breaks (DSBs), thereby regulating DNA damage response mechanism (By similarity). Also plays a role in pre-B cell allelic exclusion, a process leading to expression of a single immunoglobulin heavy chain allele to enforce clonality and monospecific recognition by the B-cell antigen receptor (BCR) expressed on individual B-lymphocytes. After the introduction of DNA breaks by the RAG complex on one immunoglobulin allele, acts by mediating a repositioning of the second allele to pericentromeric heterochromatin, preventing accessibility to the RAG complex and recombination of the second allele. Also involved in signal transduction and cell cycle control. May function as a tumor suppressor. Necessary for activation of ABL1 and SAPK. May play a role in vesicle and/or protein transport. Could play a role in T-cell development, gonad and neurological function. Plays a role in replication-dependent histone mRNA degradation. Binds DNA ends. Phosphorylation of DYRK2 in nucleus in response to genotoxic stress prevents its MDM2-mediated ubiquitination and subsequent proteasome degradation. Phosphorylates ATF2 which stimulates its function in DNA damage response. Phosphorylates ERCC6 which is essential for its chromatin remodeling activity at DNA double-strand breaks. Phosphorylates TTC5/STRAP at 'Ser-203' in the cytoplasm in response to DNA damage, which promotes TTC5/STRAP nuclear localization. Also involved in pexophagy by mediating phosphorylation of PEX5: translocated to peroxisomes in response to reactive oxygen species (ROS), and catalyzes phosphorylation of PEX5, promoting PEX5 ubiquitination and induction of pexophagy.
Synonyms: TEL1; TELO1; AT1; ATA; ATC; ATD; ATDC; ATE
Tractability: Small molecule: a structure with a bound ligand is known; a high-quality ligand is known; it belongs to a druggable protein family. PROTAC: ubiquitination databases record sites on it; its protein half-life has been measured; a small molecule that binds it is known.
Target class: Enzyme; Atypical protein kinase group; Atypical protein kinase PIKK family; Protein Kinase; Kinase
Chemical probes: AZD0156 (high quality), KU-55933 (high quality), KU-60019
Safety:
Unwanted effects reported when the protein is acted on. In parentheses: how it was acted on, where the effect was seen, and who reports it.
Ataxia (inhibition; central nervous system; source: Brennan et al. (2024))
diabetes (inhibition; metabolism; source: Brennan et al. (2024))
growth retardation (inhibition; source: Brennan et al. (2024))
immunodeficiency (inhibition; immune; source: Brennan et al. (2024))
neurodevelopmental disorder (inhibition; central nervous system; source: Brennan et al. (2024))
premature ageing (inhibition; source: Brennan et al. (2024))
speech disorder (inhibition; central nervous system; source: Brennan et al. (2024))
nausea (source: ClinPGx)
nausea and vomiting (source: ClinPGx)
vomiting (source: ClinPGx)
Gene: Protein-coding gene on chromosome 11 (108,222,804 to 108,369,102, forward strand). Ensembl gene ENSG00000149311.
Subcellular location: Nucleus; Cytoplasmic vesicle; Cytoplasm, cytoskeleton, microtubule organizing center, centrosome; Peroxisome matrix
Subcellular location (Human Protein Atlas): Nucleoplasm; Vesicles; Golgi apparatus
Pathways (Reactome):
DNA Repair: HDR through Homologous Recombination (HRR); HDR through Single Strand Annealing (SSA); Homologous DNA Pairing and Strand Exchange; Nonhomologous End-Joining (NHEJ); Presynaptic phase of homologous DNA pairing and strand exchange; Processing of DNA double-strand break ends; Recruitment and ATM-mediated phosphorylation of repair and signaling proteins at DNA double strand breaks; Resolution of D-loop Structures through Holliday Junction Intermediates; Resolution of D-loop Structures through Synthesis-Dependent Strand Annealing (SDSA); Sensing of DNA Double Strand Breaks
Disease: Defective HDR through Homologous Recombination Repair (HRR) due to PALB2 loss of BRCA1 binding function; Defective HDR through Homologous Recombination Repair (HRR) due to PALB2 loss of BRCA2/RAD51/RAD51C binding function; Defective homologous recombination repair (HRR) due to BRCA1 loss of function; Impaired BRCA2 binding to PALB2; Impaired BRCA2 binding to RAD51
Cell Cycle: Autodegradation of the E3 ubiquitin ligase COP1; G2/M DNA damage checkpoint
Cellular responses to stimuli: DNA Damage/Telomere Stress Induced Senescence; Regulation of HSF1-mediated heat shock response
Autophagy: Pexophagy
Reproduction: Meiotic recombination
Gene Ontology:
Molecular function: 1-phosphatidylinositol-3-kinase activity; DNA-dependent protein kinase activity; identical protein binding; protein binding; protein serine kinase activity; protein serine/threonine kinase activity; protein-containing complex binding; histone H2AXS139 kinase activity; kinase activity; protein kinase activity
Biological process: cellular response to gamma radiation; cellular response to nitrosative stress; cellular response to reactive oxygen species; cellular response to stress; cellular response to X-ray; DNA damage checkpoint signaling; DNA damage response; DNA double-strand break processing; double-strand break repair; double-strand break repair via homologous recombination; establishment of protein-containing complex localization to telomere; establishment of RNA localization to telomere; histone mRNA catabolic process; mitotic G2 DNA damage checkpoint signaling; mitotic spindle assembly checkpoint signaling; negative regulation of B cell proliferation; negative regulation of telomere capping; negative regulation of TORC1 signaling; peptidyl-serine autophosphorylation; pexophagy; positive regulation of apoptotic process; positive regulation of autophagosome assembly; positive regulation of cell migration; positive regulation of double-strand break repair; and 36 more
Cellular component: chromosome, telomeric region; cytoplasmic vesicle; DNA repair complex; nucleolus; nucleoplasm; nucleus; peroxisomal matrix; site of double-strand break; centrosome; chromosome; cytoplasm; cytosol; extrinsic component of synaptic vesicle membrane; spindle
Genetic constraint (gnomAD): Loss-of-function variants: 274 observed, 357.47 expected, observed/expected ratio (o/e) 0.77, 90% interval 0.69 to 0.85. The upper end of that interval is the gene's LOEUF score, 0.85, which puts it in group 3 of 6, group 1 being the genes least tolerant of losing a copy. Missense variants: 3,124 observed, 3,537.9 expected, observed/expected ratio (o/e) 0.88, 90% interval 0.86 to 0.91. Synonymous variants: 1,103 observed, 1,195.7 expected, observed/expected ratio (o/e) 0.92, 90% interval 0.88 to 0.97.
Gene-disease validity (ClinGen):
ClinGen rates the evidence that ATM causes each of these diseases.
ataxia telangiectasia (autosomal recessive): Definitive.
ATM-related cancer predisposition (autosomal dominant): Definitive. Hereditary cancer predisposition due to variation(s) in the ATM gene.
Cancer hallmarks: invasion and metastasis (suppresses); cell replicative immortality (promotes); escaping programmed cell death (promotes); genome instability and mutations (suppresses); tumour promoting inflammation (promotes)
Homologues: Orthologues: chimpanzee ATM (99% identical), macaque ATM (98% identical), dog ATM (90% identical), rabbit ATM (89% identical), pig ATM (88% identical), guinea pig ATM (86% identical), mouse Atm (84% identical), rat Atm (84% identical), tropical clawed frog atm (65% identical), zebrafish atm (54% identical). Paralogues in human: PRKDC (17% identical), ATR (14% identical), SMG1 (13% identical), TRRAP (13% identical), MTOR (13% identical).
Diseases named in the same sentence as ATM in open-access papers:
ATM is named in the same sentence as 631 diseases in open-access papers, as found by Europe PMC text mining. Sharing a sentence is not in itself a finding about the gene and the disease. The quoted sentences say what the papers report.
breast cancer (878 papers, 1997 to 2026). A primary or metastatic malignant neoplasm involving the breast. "Although certain pathogenic variants in the ATM gene, such as c.7271 T > G, are classified as “high-risk variants”, the ATM gene is generally regarded as a moderate-penetrance risk gene for breast cancer." (PMID 41528496, 2026). "Prolonging the ATM deficiency (represented as KU-p-) also seemed to cause a higher genomic instability in breast cancer observed as higher count of micronuclei in the treatments, KU-p- + ETO and ETO + KU-p-." (PMID 41557625, 2026). "Heterozygous ATM GV carriers also have an increased cancer risk, particularly of female breast cancer." (PMID 41546701, 2026). "Pathogenic germline variants in the ATM gene are associated with a 20–30% lifetime risk of breast cancer." (PMID 41596415, 2026). "We aimed to perform splicing analysis of ATM splice-site variants identified in the large-scale sequencing project BRIDGES (Breast Cancer After Diagnostic Gene Sequencing)." (PMID 41596415, 2026). "In this study, we aimed to investigate the splicing impact of +2T variants in the breast cancer susceptibility genes ATM, BRCA1, and PALB2." (PMID 41230741, 2026). "An analysis used breast cancer microsimulation models from the Cancer Intervention and Surveillance Modeling Network to compare different screening strategies for ATM, CHEK2, or PALB2 P/LP variant carriers." (PMID 39858629, 2025). "A strong association between the risk of breast cancer and family history was found for ATM, BRCA1, BRCA2, CHEK2, and PALB2 P/LP variant carriers." (PMID 39858629, 2025). "Numerous systematic reviews and meta-analyses have identified a link between ATM variants and an increased risk of breast cancer, establishing this gene as the third most common cause of hereditary cancer across different populations." (PMID 40259910, 2025). "This RAMP2-AS1/miR-660-5p/ATM axis represents a potential hypoxia-associated regulatory mechanism with prognostic significance in breast cancer." (PMID 41065894, 2025). "It has also been observed that heterozygous mutations in the ATM gene are associated with an increased risk of developing breast cancer." (PMID 40259910, 2025). "The risk of breast cancer associated with CHIP was predominantly driven by mutations in the gene ATM (OR [95% CI] = 3.97 [2.89–5.36], P = 2.02e-18), and DNMT3A (OR [95% CI] = 1.33 [1.03–1.66], P = 0.014)." (PMID 40679991, 2025). "CHIP is associated with an increased risk of breast cancer, particularly influenced by the ATM and DNMT3A genes." (PMID 40679991, 2025). "In our study, we found that mutations in DNMT3A and ATM were the most significant CHIP-associated mutations linked to breast cancer risk in both logistic and CoxPH models." (PMID 40679991, 2025). "For the BRCA1, BRCA2, PALB2, CHEK2, and ATM genes, most protein-truncating variants have been associated with a high risk of breast cancer." (PMID 39858629, 2025). "Further analysis of the ten most mutated CHIP genes revealed that mutations in DNMT3A and ATM were strongly linked to an elevated breast cancer risk." (PMID 40679991, 2025). "Research on the potential interaction of modern MHT regimens with breast cancer risk due to PVs in ATM, CHEK2, and other genes should be prioritized." (PMID 40298171, 2025). "For instance, the ATM PV-positive patient was diagnosed with breast cancer at an advanced age (79 years) and tongue cancer at 59 years, a tumor type less commonly associated with the ATM-related cancer spectrum." (PMID 41156180, 2025). "For instance, heterozygosis in PALB2, BRIP1, and ATM increases the lifetime risk of breast cancer, while homozygosis causes multisystemic genetic syndromes, such as Fanconi’s anemia (PALB2 and BRIP1) and ataxia-telangiectasia (ATM)." (PMID 39858629, 2025).
breast cancer (continued). "Other studies support the possible pathogenic effect of ATM c.1066-6T>G on either ataxia telangiectasia or breast cancer." (PMID 40507299, 2025). "Poly(ADP-ribose) polymerase (PARP) inhibitors, which exploit synthetic lethality in ATM-deficient cells, have demonstrated efficacy in treating solid tumors with ATMaberrations, such as prostate and breast cancer." (PMID 41023839, 2025). "For individuals with pathogenic ATM mutations, the relationship between radiation exposure and breast cancer risk remains complicated." (PMID 40800071, 2025). "Previous studies have suggested the missense variant NM_000051.4(ATM):c.7271T>G is associated with a high risk of breast cancer (BC), but the magnitude of the association, and the associations with other cancer types, are unclear." (PMID 40451289, 2025). "Having a breast cancer case in families with an ATM or CHEK2 variant is a prerequisite in the Netherlands for performing genetic testing in relatives, as it would otherwise not lead to any preventive options in relatives." (PMID 38722431, 2024). "Because LP/P variants in ATM are considered a relatively infrequent cause of hereditary breast cancer the genetic heterogeneity was set to 0.02: in other words, as if 2% of hereditary breast cancer cases are caused by ATM LP/P variants." (PMID 38854136, 2024). "Case-control studies with ATM pathogenic variants are expected to yield odds ratio (OR) >2 based on the known increased lifetime breast cancer risks for pathogenic variant carriers 10,11." (PMID 38854136, 2024). "Parents of children with AT are carriers of a mutation in the ATM gene, which is associated with increased risk for breast cancer." (PMID 39222344, 2024). "There is evidence both from studies of families of A-T patients, and from large case-control studies, of an association between pathogenic variants in ATM and increased risk of breast cancer, with an estimated RR of approximately twofold." (PMID 39209703, 2024). "In the present study, c.6115G>A ATM variant, was identified in 4 breast cancer cases belonging to 3 unrelated families all originating from the South of Tunisia suggesting a possible founder effect." (PMID 38313678, 2024). "The ATM missense variant c.7271T > G, initially associated with a milder phenotype of ataxia-telangiectasia (A-T), has been found to carry a substantial breast cancer risk comparable to that of BRCA2." (PMID 38397209, 2024). "For ATM variants, there was an estimated breast cancer relative risk of 2.8, and the absolute breast cancer risk reached 27% by 80 years." (PMID 38929805, 2024). "They estimated that women with heterozygous ATM mutations had a 5.1-fold increased risk of breast cancer, compared to the general population (P = 0.009)." (PMID 39543654, 2024). "And third, ATM has low penetrance for breast cancer, conveying only two-fold risk which leads to substantial phenocopy and unaffected carriers of pathogenic variants within a family." (PMID 38854136, 2024). "A systemic review showed that the prevalence of the deletion, insertion, substitution mutation variants in ATM are associated with breast cancer." (PMID 39272924, 2024). "Women carrying a heterozygous pathogenetic variant in ATM have a 20–40% lifetime risk to develop breast cancer; thus, annual mammography is recommended from 40 years." (PMID 38397209, 2024). "We found that by age 70, women with an ATM pLOF variant had a 37% accumulated risk of being diagnosed with breast cancer (HR = 4.3), aligning with the 28% to 38% lifetime risk mentioned in the NCCN guidelines." (PMID 39669587, 2024). "The allelic heterogeneity was conservatively set to 1.0: in other words, assuming that there is only one LP/P variant that causes ATM-related breast cancers." (PMID 38854136, 2024). "By age 80, the cumulative risk of breast cancer was 30% (95% CI 16% to 41%) for ATM PTV carriers and 25% (19% to 30%) for CHEK2 PTV carriers, compared with 12% in the general population." (PMID 39209703, 2024).